RN7SKP163 (RN7SK pseudogene 163)
Gene: Miscellaneous RNA gene on chromosome 6 (75,654,970 to 75,655,299, reverse strand). Ensembl gene ENSG00000200091.
Homologues: Orthologues: chimpanzee 7SK (98% identical). Paralogues in human: 7SK (71% identical), RN7SKP180 (71% identical), RN7SKP79 (71% identical), RN7SKP255 (71% identical), RN7SKP204 (70% identical), RN7SKP71 (70% identical), RN7SKP146 (70% identical), RN7SKP170 (70% identical), RN7SKP74 (70% identical), RN7SKP78 (70% identical), RN7SKP90 (70% identical), RN7SKP124 (69% identical), and 284 more.